MACF1 (microtubule actin crosslinking factor 1)
Description:
[Isoform 2]: F-actin-binding protein which plays a role in cross-linking actin to other cytoskeletal proteins and also binds to microtubules. Plays an important role in ERBB2-dependent stabilization of microtubules at the cell cortex. Acts as a positive regulator of Wnt receptor signaling pathway and is involved in the translocation of AXIN1 and its associated complex (composed of APC, CTNNB1 and GSK3B) from the cytoplasm to the cell membrane (By similarity). Has actin-regulated ATPase activity and is essential for controlling focal adhesions (FAs) assembly and dynamics (By similarity). Interaction with CAMSAP3 at the minus ends of non-centrosomal microtubules tethers microtubules minus-ends to actin filaments, regulating focal adhesion size and cell migration. May play role in delivery of transport vesicles containing GPI-linked proteins from the trans-Golgi network through its interaction with GOLGA4. Plays a key role in wound healing and epidermal cell migration (By similarity). Required for efficient upward migration of bulge cells in response to wounding and this function is primarily rooted in its ability to coordinate microtubule dynamics and polarize hair follicle stem cells (By similarity). As a regulator of actin and microtubule arrangement and stabilization, it plays an essential role in neurite outgrowth, branching and spine formation during brain development (By similarity).
Synonyms: ABP620; ACF7; KIAA0465; KIAA0754; KIAA1251; MACF; FLJ45612; FLJ46776; Lnc-PMIF; LIS9; OFC4
Tractability: Antibody: UniProt places it where antibodies can reach, with high confidence; its Gene Ontology location is reachable by antibodies, with high confidence; the Human Protein Atlas places it where antibodies can reach. PROTAC: ubiquitination databases record sites on it; its protein half-life has been measured.
Gene: Protein-coding gene on chromosome 1 (39,081,316 to 39,487,177, forward strand). Ensembl gene ENSG00000127603.
Subcellular location: Cytoplasm, cytoskeleton (Isoform 2); Cytoplasm; Golgi apparatus; Cell membrane; Cell projection, ruffle membrane; Cytoplasm (Isoform 1); Cytoplasm, cytoskeleton
Subcellular location (Human Protein Atlas): Actin filaments; Plasma membrane; Basal body; Cell Junctions
Gene Ontology:
Molecular function: actin binding; actin filament binding; cadherin binding; microtubule minus-end binding; protein binding; RNA binding; structural molecule activity; calcium ion binding; microtubule binding
Biological process: Golgi to plasma membrane protein transport; positive regulation of axon extension; regulation of cell migration; regulation of focal adhesion assembly; regulation of microtubule-based process; intermediate filament cytoskeleton organization; positive regulation of Wnt signaling pathway; regulation of epithelial cell migration; regulation of neuron projection arborization; wound healing; establishment of protein localization to membrane; regulation of anatomical structure morphogenesis; regulation of cell projection organization; regulation of multicellular organismal process
Cellular component: actin cytoskeleton; cytoplasm; Golgi apparatus; microtubule; plasma membrane; ruffle membrane; cytoskeleton; intermediate filament; membrane; cell leading edge
Genetic constraint (gnomAD): Loss-of-function variants: 174 observed, 828.95 expected, observed/expected ratio (o/e) 0.21, 90% interval 0.19 to 0.24. The upper end of that interval is the gene's LOEUF score, 0.24, which puts it in group 1 of 6, group 1 being the genes least tolerant of losing a copy. Missense variants: 7,464 observed, 9,087.4 expected, observed/expected ratio (o/e) 0.82, 90% interval 0.81 to 0.84. Synonymous variants: 3,083 observed, 3,308.6 expected, observed/expected ratio (o/e) 0.93, 90% interval 0.9 to 0.96.
Gene-disease validity (ClinGen):
ClinGen rates the evidence that MACF1 causes each of these diseases.
lissencephaly spectrum disorder with complex brainstem malformation (autosomal dominant): Moderate.
Homologues: Orthologues: chimpanzee MACF1 (99% identical), rabbit MACF1 (89% identical), pig MACF1 (89% identical), dog MACF1 (89% identical), guinea pig MACF1 (84% identical), rat Macf1 (83% identical), mouse Macf1 (82% identical), macaque MACF1 (71% identical), tropical clawed frog macf1 (59% identical). Paralogues in human: DST (46% identical), SYNE1 (15% identical), PLEC (14% identical), SYNE2 (11% identical), UTRN (8% identical), DMD (8% identical), SPTBN1 (8% identical), SPTBN2 (7% identical), SPTB (7% identical), SPTBN5 (7% identical), DSP (7% identical), SPTBN4 (7% identical), and 24 more.
Diseases named in the same sentence as MACF1 in open-access papers:
MACF1 is named in the same sentence as 103 diseases in open-access papers, as found by Europe PMC text mining. Sharing a sentence is not in itself a finding about the gene and the disease. The quoted sentences say what the papers report.
breast carcinoma (11 papers, 2014 to 2023). "MACF1 mutations were associated with upregulation of the mTOR signaling pathway and had a worse prognosis in breast cancer." (PMID 36779847, 2023). "Recently, the MACF1 mutation was found to be a potential prognostic biomarker and therapeutic target for breast cancer." (PMID 37589509, 2023). "MACF1 was also linked to breast cancer by a genome-wide DNA methylation profiles analysis and was speculated to regulate cell motility." (PMID 29587367, 2018). "MACF1 also plays a role in cytoskeleton organization in cells, which contributes to tumor progression, and the abnormal expression of MACF1 initiates proliferation, metastasis, and migration in breast cancer." (PMID 35205681, 2022). "A systematic investigation of the roles of + TIP proteins in EMT and migration also revealed a determinant role for MACF1 in breast cancer progression." (PMID 33816492, 2021). "In vivo experimental metastasis assays in mice have also shown a robust decrease in lung metastasis when MACF1 was depleted, revealing a role for MACF1 in the metastatic progression of breast cancer." (PMID 33816492, 2021). "Although this study highlighted for the first time a potential role for MACF1 in breast cancer, investigations in in vivo models are warranted to determine if MACF1 is an important contributor of HER2-induced breast cancer progression and metastasis." (PMID 33816492, 2021). "The role of MACF1 as a potential metastatic regulator was also investigated both in breast cancer and melanoma." (PMID 33816492, 2021). "The main reason is that katanin P80 can affect the migration and proliferation of cells through targeting a number of genes and pathways, such as MACF1 and LAPSER1 genes, consequently increasing the level of lymph node metastasis in breast cancer patients." (PMID 36934373, 2023). "Genes extracted from the mRNA dataset, which show great significance in the development of breast cancer, are CENPA, MACF1, UGT2B7 and SEMA3B." (PMID 35205681, 2022). "Using a shRNA screen that depleted most + TIPs in the metastatic breast cancer cell line MDA-MB-231, MACF1 was the only candidate found to play a role in both cell migration and the EMT state." (PMID 33816492, 2021).
schizophrenia (10 papers, 2015 to 2025). A major psychotic disorder characterized by abnormalities in the perception or expression of reality. "In 2007, Camargo and colleagues identified MACF1 as a protein interacting with two schizophrenia risk genes, DISC1 (disrupted in schizophrenia 1) and DTNBP1 (dysbindin)." (PMID 39781307, 2024). "MACF1 is known to be involved in neurite growth during brain development and has previously been linked to schizophrenia." (PMID 38306997, 2024). "The overlapping risk of BPAD and schizophrenia with MACF1 has also been established through other variants found in schizophrenia and through the interactions between MACF1 and DISC-1 (Disrupted in Schizophrenia)." (PMID 37353479, 2023). "MACF1 variants are associated with the neurological pathologies Parkinson's disease, autism and schizophrenia." (PMID 31190668, 2019). "Recently, it was also reported that the MACF1 gene is a strong candidate susceptibility gene for schizophrenia, based on the identification of de novo mutations in schizophrenic patients." (PMID 28150729, 2017). "On the top of the list, both LRP1 and MACF1 genes are supported by 5 out of 6 independent evidences, suggesting their high pathogenic potential for schizophrenia." (PMID 26666178, 2015). "We hypothesize that the co-segregation of these duplications with the rare variant g.39914279 C > G of MACF1 gene precipitated with schizophrenia and schizoaffective disorder." (PMID 33897758, 2021). "Of 8 genes showing more than two supporting evidences for pathogenic prediction, some of genes (e.g. LRP1, MACF1, DICER1 and ABCA2) harbours de novo mutations provided promising evidence as a strong candidate genes for schizophrenia." (PMID 26666178, 2015). "Additionally, MACF1 was found to be hyper-methylated in a cohort of patients with first-episode psychosis with presumed schizophrenia diagnoses." (PMID 37353479, 2023). "In addition, the MACF1 gene is enriched significantly within brain specific critical exons, and the LRP1 gene ranked top 20 in list of schizophrenia-associated loci in the recent large-scale GWAS2." (PMID 26666178, 2015). "Microtubule-actin crosslinking factor 1 (MACF1), is known to play an important role in regulating cytoskeleton dynamics, cell migration, growth and differentiation, and its abnormal expression has been closely connected to schizophrenia, Parkinson’s disease, cancer and osteoporosis." (PMID 34621291, 2021).
Parkinson disease (8 papers, 2015 to 2024). A progressive degenerative disorder of the central nervous system characterized by loss of dopamine producing neurons in the substantia nigra and the presence of Lewy bodies in the substantia nigra and locus coeruleus. "Neuronal deletion of MACF1 impairs proliferation and differentiation capability, and is likely to cause Parkinson’s disease among the elderly." (PMID 32143362, 2020). "Reduction or depletion of MACF1 disorganizes the cytoskeleton and impairs cellular functions, and further confers risk for degenerative diseases such as inflammatory colitis and Parkinson’s disease." (PMID 32143362, 2020). "The duplication of a region on chromosome 1p34.3 where MACF1 is located was identified as the only chromosomal abnormality detected in a patient suffering from a neuromuscular condition, while genetic variations of MACF1 have been correlated with increased risk of Parkinson’s disease." (PMID 29373494, 2018). "MACF1 has been involved in the pathogenesis of Parkinson disease, since it has been observed that PD patients have lower MACF1 mRNA levels than controls, leading to dysregulation of the cytoskeleton in dopaminergic neurons." (PMID 32033020, 2020).
bipolar disorder (7 papers, 2021 to 2025). A disorder of the brain that causes unusual shifts in mood, energy, activity levels and the ability to carry out day-to-day tasks. "The mutation of MACF1 found in the patient with bipolar disorder is a frameshift mutation (p.V266fs) in an exon specific for a splice variant (ENST00000496804), which is predicted to result in nonsense-mediated mRNA decay (NMD)." (PMID 34100076, 2021). "In this study, we focused on two de novo LOF mutations in calcium-related genes, EHD1 and MACF1, found in patients with bipolar disorder." (PMID 34100076, 2021). "Here, we report that the mutation causing truncation of EHD1 results in LOF and dominant negative effects, and mutations in both EHD1 and MACF1 cause behavioral changes similar to those in previously proposed mouse models of bipolar disorder." (PMID 34100076, 2021). "MACF1 dysregulation or mutations have been linked to neurological diseases including Parkinson’s disease (PD), autism spectrum disorder (ASD), bipolar disorder and schizophrenia." (PMID 39198412, 2024). "New evidence also points to a role of MACF1 in the etiology of bipolar disorder and psychosis." (PMID 40779003, 2025). "Second, we generated two heterozygous knock-in mouse lines with the mutations of Macf1 and Ehd1 using CRISPR/Cas9 and performed behavioral screening using IntelliCage and long-term recording of wheel running, which has been used to assess bipolar disorder-like phenotypes of mouse models." (PMID 34100076, 2021).
glioblastoma (6 papers, 2018 to 2022). The most malignant astrocytic tumor (WHO grade IV). "Further suppression of MACF1 in glioblastoma cells inhibited cell proliferation and migration associated with reduced Axin1 and β-catenin, which are Wnt signaling mediators." (PMID 29587367, 2018). "Due to its high expression in the brain and its function as a cytoskeletal cross-linking protein, the role of MACF1 was investigated in brain tumors such as glioblastoma (GBM)." (PMID 33816492, 2021). "Further, downregulation of MACF1 increased sensitivity of glioblastoma cells to the DNA alkylating agent temozolomide." (PMID 30618566, 2018). "While most findings indirectly show the role of MACF1 in cancers, Quick’s group was the first to provide direct evidence of MACF1’s function in glioblastoma." (PMID 29587367, 2018). "The authors showed that MACF1 knock-out could reduce proliferation and migration of glioblastoma cells, which was accompanied by a reduction in WNT signaling effectors." (PMID 30618566, 2018). "MACF1 expression was also prominent at advanced stages in brain tumors, including glioblastoma." (PMID 30618566, 2018). "Furthermore, our work revealed that downregulating MACF1 expression reduced glioblastoma cell proliferation and migration, which was also accompanied by reductions in Axin and β-catenin expression, which are mediators of Wnt signaling." (PMID 29373494, 2018). "Since overexpression of the Teneurin-1-ICD increased resistance to this drug in glioblastoma, interaction of Teneurin-1 and MACF1 might contribute to this phenotype, possibly involving the stabilization of actin and microtubule cytoskeletal structures and WNT signaling activity." (PMID 30618566, 2018). "They found that MACF1 was predominately expressed in glioblastomas but not in either normal brain tissue or lower-grade brain tumors." (PMID 29587367, 2018). "Of some concern, MACF1 (microtubule actin cross-linking factor 1) was found to be predominately elevated in grade III-IV astrocytomas and grade IV glioblastoma, however when treated with TMZ, MACF1 is reduced and diminishes GBM cell proliferative capacity." (PMID 35053843, 2022).
osteoporosis (6 papers, 2020 to 2026). A condition of reduced bone mass, with decreased cortical thickness and a decrease in the number and size of the trabeculae of cancellous bone (but normal chemical composition), resulting in increased fracture incidence. "Our study showed that FoxO1 responded to chronic oxidative stress induced by MACF1 deficiency to determine β‐catenin fate and regulate osteoblast differentiation during senile osteoporosis." (PMID 41363907, 2026). "We subsequently validated the relationship of miR-138-5p with the target gene microtubule actin cross-linking factor 1 (MACF1) in aged osteoblast differentiation and senile osteoporosis by loss- and gain-of-function of miR-138-5p in vitro." (PMID 35982896, 2022). "And we have found that MACF1 expression was associated with the reduction in osteogenesis in ageing‐related osteoporosis." (PMID 34133068, 2021). "The reduction in bone formation in ageing‐related osteoporosis was caused by decreased MACF1 level leading to disabled suppression of HES1 expression." (PMID 34133068, 2021). "Loss of MACF1 decreases bone mass and quality in adult mice, which confers risk for degenerative bone diseases such as osteoporosis and fracture." (PMID 32143362, 2020). "In summary, these results suggest that MACF1 positively regulates bone mass and bone quality in mice, and loss of MACF1 confers risk for degenerative phenotypes such as osteoporosis and fracture." (PMID 32143362, 2020). "In summary, we discovered new roles of MACF1 in regulating osteogenic differentiation and bone formation, and that loss of MACF1 in bone forming cells impairs osteogenic functions and then leads to degenerative bone disorders such as osteoporosis." (PMID 32143362, 2020). "During the aging process, bones become osteoporotic and fragile, and mesenchymal MACF1’s downregulation in osteoporotic patients suggest that, in the progression of primary osteoporosis, functional deficiency of MACF1 might be a key cause." (PMID 32143362, 2020). "More importantly, they revealed the regulatory effect of MACF1 on the FoxO1/β‐catenin pathway, osteoblast function, and mechanisms of aging‐related osteoporosis." (PMID 41363907, 2026). "In our previous investigation, we observed that the expression of MACF1 in the femoral tissue of elderly patients with osteoporosis exhibited an age‐dependent decline." (PMID 41363907, 2026). "The in situ injection of MACF1 plasmid showed that the forced expression of MACF1 can rescue aging-related osteoporosis and post-menopausal osteoporosis." (PMID 40244019, 2025). "In summary, the current findings identify a new aging-related miRNA, miR-138-5p, that negatively modulates osteoblast differentiation and bone formation in senile osteoporosis by targeting MACF1." (PMID 35982896, 2022). "In a recent study, we found that the expression of MACF1 decreased with age in femur tissues of patients with aging-related osteoporosis, and overexpression of MACF1 alleviated the decrease in bone formation and osteoporosis in aged mice." (PMID 35982896, 2022). "Through this study, we have discovered the relationship and mechanism between MACF1 and ageing‐related osteoporosis." (PMID 34133068, 2021). "The function of MACF1 in both osteoporosis models has proved the rescuing function of MACF1 on osteoporosis." (PMID 34133068, 2021). "Enhancing the expression of MACF1 by plasmids would efficiently rescue bone formation in ageing‐related osteoporosis and post‐menopausal osteoporosis mice." (PMID 34133068, 2021). "This study has investigated the expression pattern of MACF1 in bone tissues of ageing‐related osteoporosis patients and ageing mice." (PMID 34133068, 2021). "Through all these results, we have firstly proved that MACF1 act as an important regulator for ageing‐related osteoporosis." (PMID 34133068, 2021).